ACTA2 (actin alpha 2, smooth muscle)
Diseases named in the same sentence as ACTA2 in open-access papers (continued):
Sharing a sentence is not in itself a finding about the gene and the disease.
cancer (144 papers, 2011 to 2026). A tumor composed of atypical neoplastic, often pleomorphic cells that invade other tissues. "This revealed that genetic Npy1r ablation did not significantly alter the abundance of stromal cell populations or ECM including cancer-associated fibroblasts [αSMA (ACTA2) and PDGFRB; fig." (PMID 40073121, 2025). "In particular, the 3D compartment is composed of a mixed population of CD206 + /CD163+ macrophages and fibroblasts expressing ACTA2/PDGFBRbeta which are known as distinctive for cancer associated fibroblasts." (PMID 40157906, 2025). "Under the predicted condition, we found the Acta2 gene, a known marker of cancer-associated fibroblasts, played a role in competitive interactions between cells with different DSB burdens." (PMID 39720517, 2024). "The role of cancer-associated fibroblasts (CAFs) in the immune microenvironment was acknowledged by selecting marker genes ACTA2, FAP, PDGFRB, and NOTCH321–23, aiding in dimensionality reduction for the clustering analysis, which identified five CAF clusters." (PMID 38740918, 2024). "The circa 1500 fibroblasts clustered in three groups (ACTA2+ myofibroblast-like cancer-associated fibroblasts [CAFs], ECM-producing CAFs, and “resting” CAFs)." (PMID 37190121, 2023). "While expression of ACTA2 – a marker expressed by both myoepithelial cells and cancer-associated fibroblasts (CAFs) – significantly increased in CAS compared to normal stroma, expression of TP63, CHD3, MYH11, SERPINB5 and MME did not increase." (PMID 37391533, 2023). "α–Smooth muscle actin ([αSMA]; encoded by ACTA2)-positive FbS3 myofibroblasts were mostly present in the submucosa of the inflamed normal, metaplastic, and dysplastic/cancer tissues." (PMID 37196797, 2023). "Apart from immune cells, the authors identified three subtypes of cancer-associated fibroblasts (CAFs), surprisingly with depleted expression of ACTA2 (a common CAF marker in most cancers)." (PMID 35669415, 2022). "ACTA2, a marker for activated pancreatic stellate cells and cancer-associated fibroblasts, was detected in all organoid lines at very low levels." (PMID 32492856, 2020). "Among those genes, we found up-regulation of αSma/Acta2, a marker of activated and cancer-associated fibroblasts, and Nidogen-2, Lamb2, and Prelp, which encode for ECM-associated proteins." (PMID 29725010, 2018). "ACTA-2 encodes smooth muscle actin, essential for muscle contraction and tissue integrity, and its reduction is relevant because it is involved in fibrosis, vascular disorders, and cancer, where cytoskeletal dynamics and cell mobility are key." (PMID 41008631, 2025). "From these clusters, five major cell types were identified via classical cell markers, including T cells (CD3E, CD8A, CD3D), B cells (CD19, MS4A1, CD79A), myeloid cells (CD14, CD68, LYZ), endothelial cells (PECAM1, VWF, CDH5) and cancer-associated fibroblasts (CAFs) (ACTA2, FAP, PDGFRB)." (PMID 39941131, 2025). "Further, cancer-associated fibroblasts were annotated based on the expression of ACTA2 and TAGLN32." (PMID 39149248, 2024). "The cells were further annotated as specific cell type subpopulations according to the expression of classic markers, including T cells (CD3D+), myeloid cells (CD68+), endothelial cells (CD34+), hepatocytes (ALB+), B cells (CD79A+), and cancer-associated fibroblasts (CAFs) (ACTA2+)." (PMID 37383234, 2023). "Specifically, according to canonical markers, the three quantity-predominant major components (i.e., c1, c2, and c4) were defined as cancer-associated myofibroblasts (CAFmyo), inflammatory CAFs (CAFinfla), and adipogenic CAFs (CAFadi) by over-presenting ACTA2, FAP/TGFB1, and CFD, respectively." (PMID 36333338, 2022). "Importantly, this group of fibroblast cells expressed the markers for cancer‐associated fibroblasts (CAFs) including ACTA2 (encoding α‐SMA), PDGFRA, PDGFRB, DDR2, FAP, and CAV1." (PMID 34459128, 2021).
cancer (continued). "With regard to the CAF model, patient-derived normal and according cancer-associated fibroblasts revealed a conserved gene expression, defined by increased transcript levels of ACTA2, COL1A1, TNC, VEGFA and ALDH1A3, with concomitant decreased expression of CAV1, CD44 and VIM in CAFs." (PMID 28372546, 2017). "Within the list of top differentially expressed genes, in the UCHL1 KDs we found downregulation of the Wnt targets POSTN, SP7, and DLL1, of the transporter ABCA4, of the homeobox gene DLX4, and of genes recently linked to cancer progression ACTA2, AQ4, GRAP2, and ALK." (PMID 28472177, 2017). "The shift in CLU+/SMA+ CAF ratios in human patients, and the shift in Clu vs. Acta2 expression in PSCs conditioned by Brca2-deficient cancer cells, suggest that CAFs of BRCA-mutated tumors may undergo a shift from myofibroblastic to immune-regulatory functions." (PMID 36316305, 2022). "Strikingly, Dkk3‐null cancer cells led to an increase in myCAF gene expression (ACTA2, CTGF, PDGFRB), with concomitant downregulation of inflammatory CAF markers (CXCL12, CXCL2) in PSCs." (PMID 41147409, 2026). "Additional clustering and dimensionality reduction, utilizing four marker genes (ACTA2, FAP, PDGFRB, and NOTCH3), resulted in the delineation of four cancer-associated fibroblast (CAF) subpopulations." (PMID 40589759, 2025). "We identified a population of cancer-associated fibroblasts (CAFs), marked by the expression of genes such as COL1A1, COL3A1, COL11A1, and ACTA2, which are known to contribute to the activation of EMT programing." (PMID 40950184, 2025). "In the presence of IgG, cancer cell CM with progranulin induced the expression of myMAF genes, including Spp1, Acta2, and Postn, while the neutralisation of LIF partially suppressed this induction." (PMID 38678021, 2024). "Studies have shown that upregulation of MYL9 and ACTA2 promotes migration in most cancers, but their downregulation promotes migration in a few cancers." (PMID 37251946, 2023). "Markers of late differentiation we identified in GBM CAFs such as ACTA2 have been identified in late-stage differentiated breast CAFs, underpinning that CAFs undergo similar differentiation trajectories across cancer entities." (PMID 36856115, 2023). "The subpopulation of FAP+ACTA2+ CAFs was composed of 276 cells (59.6%) from indolent LUADs and 187 cells (40.4%) from aggressive carcinomas." (PMID 37848457, 2023). "Summary of top four selected genes (COL5A2, ITGAV, SPARC and ACTA2) which were correlated with EMT signature in 32 pan cancer cohorts was presented in radar graphs, and the well-known CDH1 (Epithelial) and VIM (Mesenchymal) genes were included as controls." (PMID 35046456, 2022). "Cluster 0 cells showed fibroblast signatures (RGS5 and NDUFA4L2), cluster 2 cells had strong expression of cancer associated fibroblast (CAF) markers (LUM, SFRP4, and COL1A1), and cluster 5 cells expressed myofibroblast markers (MYH11, TAGLN, and ACTA2)." (PMID 33662621, 2021). "The expression of CDH6, DPYSLE3, GJA1, IL15, and ACTA2 is also relevant to survival in many types of cancers, but its mechanism of action in CRC requires further study to explore its impact." (PMID 34211976, 2021). "For stroma, the marker genes used were VWF, ENG, and CDH5 (for endothelial cells), DCN, ACTA2, and FAP (for cancer-associated fibroblasts), and PTPRC, CD4, and CD163 (for leukocytes)." (PMID 33810510, 2021). "We and others have shown that ACTA2 positive cells, identified as CAFs in other cancers, are found in CLL lymph nodes." (PMID 31200555, 2019). "Among the tdT+ IASs, 10/15 expressed ACTA2, suggesting that some ACTA2-expressing cells turned off ACTA2 while giving rise to cancer reactive stroma." (PMID 27935821, 2017). "Furthermore, fibroblasts exposed to CC cells typically undergo conversion to cancer-associated fibroblasts (CAFs), as evidenced by increased CAF markers (e.g., ACTA2, FAP, COL1A2, VIM)." (PMID 40055606, 2025).
cancer (continued). "Based on previous studies, Fibro_FAP was classified as inflammatory cancer-associated fibroblast (iCAF)-like, Fibro_ACTA2 as myofibroblastic cancer-associated fibroblast (myCAF)-like, and Fibro_HLA-DRA and Fibro_AGR2 as antigen-presenting cancer-associated fibroblast (apCAF)-like." (PMID 39722065, 2025). "The transcriptomic analysis confirmed mRNA expression of classical epithelial markers (cytokeratins, claudins, EpCAM, E-cadherin) in the SW480 cancer cell mono-spheroids and typical fibroblast markers (ACTA2/α-SMA, FAP-α, PDGFR, and MRC2) in the fibroblast mono-spheroids." (PMID 39011470, 2024). "For example, the stromal subset consisted of endothelial cells identified by expressions of VWF, PECAM1 and KDR, pericytes with high RGS5, ACTA2, and COL4A1 expressions, and cancer-associated fibroblasts (CAFs) identified by significant expressions of COL1A1, DCN and LUM." (PMID 38925650, 2024). "Using scRNA-seq data, we investigated the expression of genes involved in stromal-like signature (FAP, VIM, and ITGB1); cancer-associated fibroblasts (CAFs; POSTN and ACTA2); as well as COL1A1, SULF1, TCF21, and DLK1, which were previously associated with FAP-high or FAP-low CAF phenotypes in OC." (PMID 39634630, 2024). "APOD, ACTA2, PDK4 and SAPCD2 have all been linked to the development of cancer in several studies." (PMID 38436027, 2024). "Moreover, a study has shown that PGAM1 interacts with ACTA2 (unrelated to its metabolic activity) to promote actin filaments assembly, cancer cell migration, and cell motility." (PMID 37542027, 2023). "Noticeable is that ACTA2 and COL1A1 are also the markers of cancer-associated fibroblasts (CAFs)." (PMID 37228646, 2023). "This second cluster could represent a cancer-associated fibroblast (CAF) population characterized by low expression of MSLN and WT1 and high expression of ACTA2, S100A4, COL5A2, SPARC, and FN1." (PMID 36901697, 2023). "Likewise, low expression levels of CDH1 and high expression levels of VIM and ACTA2 in cancer cells indicate the high metastatic potential of cancers and correlate with the poor prognosis of affected patients." (PMID 35621926, 2022). "C12, highly expressed ACTA2, VIM, and FGF9, was recognized as cancer-associated fibroblasts (CAFs)." (PMID 35523772, 2022). "Besides the general roles of neural stemness genes in promoting cancer, expression of Acta2, Desmin or Kdr is frequently observed during cancer progression, and Afp is used as a marker for cancers of the liver, testicles and ovaries." (PMID 33468253, 2021). "The fibroblasts encompassed 4 major populations defined by key cancer-associated fibroblast (CAF) markers, including fibroblast activation protein (FAP), alpha smooth muscle actin (αSMA, ACTA2), podoplanin (PDPN), and platelet-derived growth factor receptor beta (PDGFRβ)." (PMID 34385456, 2021). "Moreover, Kaplan–Meier analysis of the cancer specific survival showed a significant correlation between patients with high versus low IL6/ACTA2 expression (HR = 2.738, 95% CI = 1.056–7.099, *P = 0.0471)." (PMID 30744595, 2019). "As SM is significantly reduced in PB-MYC tumors, we used GIFM to test whether ACTA2+ cells are lost or change fate into cancer-reactive stroma." (PMID 27935821, 2017). "Moreover, we showed, in TCGA network of variant cancers and the ovarian microdissected profile, that SNAI2 was positively related with classical CAF activation markers, such as ACTA2, FAP, and PDGFRB." (PMID 29041931, 2017). "As TRAMP tumors have a large increase in SM, and stromal cells invade into IASs, we also fate-mapped the Acta2-lineage cells in TRAMP mice to test whether they expand only in the SM layer or give rise to other cancer reactive stroma." (PMID 27935821, 2017).
cancer (continued). "Further examination on several genes involved in the cancer growth showed that the expressions of hepatocyte growth factor (HGF), fibroblast associated protein (FAP) and alpha smooth muscle actin 2 (ACTA2) were significantly increased in CD90+ subpopulation (p<0.05)." (PMID 24116172, 2013). "Likewise, while cancer cell CM alone suppressed a myMAF signature, the addition of recombinant progranulin restored expression of several myMAF genes, including Ctrhc1, Spp1, Acta2, and Postn, while downregulating a vMAF signature." (PMID 38678021, 2024). "The RT-qPCR analysis indicated that mRNA expression of CAF markers (ACTA2, TAGLN, and LIF) was increased when fibroblasts were educated by cancer cells (gray bars, cancer-EV + CAF)." (PMID 39261905, 2024). "Our analyzis identified shared markers among the fibroblasts from both carcinoma types, notably DCN, VIM, ACTA2, CXCL12/14, and COL1A1, which were prominent markers, characteristic of these cells." (PMID 39796089, 2024). "Mesenchymal migration, induced by lamellipodia formation, is a type of cancer cell migration, and we verified that either ACTC1 or ACTA2 KD significantly reduced lamellipodia formation." (PMID 37891844, 2023). "Most cancers presented PDGFRA, PDGFRB, PDPN, ACTA2, and FAP hypermethylation compared to normal samples." (PMID 36032075, 2022). "We next examined the interactions between WISP2 and other proteins using GeneMANIA database for cancer genomics database, illuminating a strong interaction among WISP2, connective tissue growth factor (CTGF), and ACTA2." (PMID 34497155, 2021). "Our results indicate that ACTA2 is activated by the CREBBP-induced acetylation, which can potentially promote the invasive ability of cancer cells by the activation of cell migration in early stage LSCC." (PMID 31217907, 2019). "Characteristic fibroblast activation gene targets such as ACTA2, COL1A1 and TNC were significantly upregulated in CAFs together with typical cancer-induced chemokines most prominently CXCL12, which has been reported for this cell line." (PMID 28372546, 2017). "We screened for cancer cells expressing at least one EMT marker, such as ACTA2, EPCAM, CD44, THY1, VIM, FN1, ZEB1 or CDH1." (PMID 29079795, 2017). "Once cancer cells arrive in the new soft environment of the lung, they release soft EVs that transform the resident fibroblasts toward a CAF phenotype through increased expression of ACTA2, COL1A1, and VEGFA, VIM." (PMID 38630893, 2024). "These MYCN-absent regions clearly co-expressed the myofibroblast markers Tagln and Acta2, consistent with the idea that these mesenchymal cells are fibroblasts and not cancer cells." (PMID 38898465, 2024). "During wounding or invasion of cancer cells, such CD34+ stromal cells may transdifferentiate into ACTA2+ myofibroblasts." (PMID 37190121, 2023). "Additionally, ESCC biomarkers identified in previous study, such as ACTA2, ANXA1, HSPA9, THBS1 etc. were also detected in EESCC, indicating the key events in advanced-stage cancer happened as earlier as in the early-stage cancer." (PMID 35397555, 2022). "ACTA2, which is highly expressed in carcinomas, is not upregulated in MF fibroblasts compared to their normal counterparts." (PMID 33941102, 2021). "In addition, several genes that were reported to be related to a less cancer aggressiveness or metastatic potential were found to be increased upon PAGE4 overexpression, including ACTA2, FBLN1 and F2R." (PMID 30658679, 2019). "The artery markers, Acta2 and Elastin, were significantly up-regulated in response to osteolytic cancer cells, however, not in response to osteoinductive cancer cells." (PMID 29988965, 2018). "Together, these results suggest that soft vesicles produced by newly disseminated cancer cells in the soft microenvironment of the lung are significantly more effective at producing a CAF-like phenotype in lung fibroblasts via ensuing upregulation of S100 inflammatory signals and ACTA2//VEGFA/VIM." (PMID 38630893, 2024).
cancer (continued). "Positive correlation with cancer-promoting genes BCL2, BCLxL, HIF1A, VEGFA, ACTA2, CCL2, PTGS2, and CDKN1A, but not Ki67, was demonstrated, particularly for ILs’ receptors." (PMID 32512917, 2020). "When looking into the CAF markers more specifically, COL1A1, ACTA2, and alpha-SMA are not significantly different in cancer tissues, compared to adjacent lung tissues, partially proving their roles may be allocated to the TME subgroup, not in whole cancer tissues or lung tissues." (PMID 39034310, 2024). "Although ACTA2+ myofibroblasts are more or less absent from PMDs (with the exception of OSMF), non-ACTA2 fibroblasts, as well as any other fibroblast cell types that may exist in cancer, are rarely investigated." (PMID 37190121, 2023).
infection (11 papers, 2011 to 2025). The state of being infected such as from the introduction of a foreign agent such as serum, vaccine, antigenic substance or organism. "After the onset of oviposition following challenge infection, fibrosis-associated genes (il-4, il-13 and acta-2) are increasingly expressed." (PMID 36923416, 2023). "MA10 infection resulted in six additional down-regulated (Cpe, B2m, Pltp, Sparc, Cldn5, Vtn) and four up-regulated DEGs (Slc2a1, Vim, Apod, Acta2), whereas Aβ pathology alone produced one down-regulated (Slc2a1) and three upregulated DEGs (Gfap, Psen1, Clu)." (PMID 41497643, 2025). "Because the half-life of Acta2 mRNA is estimated at ~18 h, and the half-life of Acta2 protein is ~59 h23, the transduced fibroblasts were analyzed at 4-days post-infection." (PMID 30413725, 2018). "HRM analysis confirmed that infection of HCjE cells with Ct results in a decrease in ACTA2 methylation, although to a lower extent than in MSP analysis (from 15% in control to 11% in Ct-infected cells)." (PMID 28660176, 2017). "The contribution of stellate cells—whose markers of the activated form are Acta2, Col1a1, Tagln, Col1a2, Col3a1, Sparc, and Rbp1—changed significantly only during infection with C. sinensis compared to the control (pairwise Kruskal–Wallis test with Benjamini–Hochberg correction, Padj = 0.030)." (PMID 39652576, 2024). "“PI3K/AKT” and “Integrin signalling” were significant in IPA of the IA-H/S data set and several infection-associated genes involved in integrin signalling, possess differences in the number of TashAT2 binding motifs between the two genomes (LAMC1, ACTA2, ITGA4 and ITGB5)." (PMID 35061738, 2022). "This was accompanied by the Acta2 gene activation at all stages of infection, with a significant increase at week 52, which may indicate the ongoing activation of fibroblastic processes even at such late stages of infection." (PMID 36355906, 2022). "At day 5 post-infection, both the secretory and the stromal compartments of the ventral prostate were conserved in the castrated animals as judged by PBP and ACTA2 expressions." (PMID 30233581, 2018). "However, infection of MLH co-culture by HCV or HIV had altered neither ACTA2 (Smooth muscle aortic alpha-actin) gene transcript levels nor αSMA proteins expression levels in LX-2 cells, determined by quantitative RT-PCR and FACS analysis, respectively." (PMID 30679661, 2019). "Of those tested Cdc42ep3 (CDC42 effector protein), ARHGDIB (Rho GDP dissociation inhibitor (GDI) beta), Acta2 (Alpha actin 2), Egr2 (Early growth response 2), IL-6 (Interleukin 6) and Vav3 (vav 1 guanine nucleotide exchange factor), were induced by EPEC infection but not by infection with EPEC Δtir." (PMID 21490959, 2011).